DNMT1 (DNA methyltransferase 1)
Diseases named in the same sentence as DNMT1 in open-access papers (continued):
Sharing a sentence is not in itself a finding about the gene and the disease.
breast tumors (18 papers, 2008 to 2024). "Combined with EGCG, sulforaphane reduces breast tumor cell proliferation through the inhibition of both DNMT1 and HDAC1 activity, which increases ERα expression compared to single treatments." (PMID 39858410, 2024). "IGF 1 binding to IGF 1R leads to downregulation of miR152 which elevates DNMT1 levels and also by activating Akt and subsequent nuclear translocation of GSK3 leading to prevention of proteasomal degradation of DNMT1 in breast tumors." (PMID 33604794, 2021). "Nonetheless, these data suggest that targeting DNMT1 in breast tumors can upregulate MHC-I mediated antigen presentation and tip the balance at equilibrium to elicit a CD8+ T cell response which promotes tumor regression and anti-tumor immunity." (PMID 29339738, 2018). "Moreover, sulforaphane reduces the activity of DNMTs, mainly DNMT1, -3a, and -3b, in cervical, prostate, and breast tumor cell lines, restoring the expression of several silenced genes, like cyclin D2 and PTEN, by demethylating their promoters." (PMID 39858410, 2024). "More importantly, a recent study showed that DNMT1 is up-regulated in breast tumors." (PMID 33616161, 2021). "Moreover, we compared FOXO3a, FOXM1, SOX2, and DNMT1 expression in a tissue microarray containing 100 independent primary breast tumor samples and 32 adjacent normal breast tissues by immunohistochemistry." (PMID 31296961, 2020). "Similar to ERRα loss-of-function in BC cells, SKBR3 cells treated with lapatinib, a dual epidermal growth factor receptor (EGFR)/human EGFR-2 (HER2) tyrosine kinase inhibitor approved for patients with HER2-amplified breast tumors, decreased both ERRα and DNMT1 protein levels." (PMID 32855526, 2020). "Previous study indicated that DNMT1, DNMT3A, and DNMT3B are upregulated in breast tumor tissues compared with normal breast tissues." (PMID 36982660, 2023). "According to the known biological observations, the most significant change occurs in the expression of DNMT1 and RUNX3 in different types of malignancies including breast tumor." (PMID 35898303, 2022). "The TSS activity of DNMT1 and DNMT3A were highest in triple negative MDA-MB-453 among breast tumor cell lines." (PMID 33604794, 2021). "Elevated expression of DNA methyltransferases (DNMTs), mainly DNMT1 and DNMT3B, has been reported to be largely responsible for the aberrant WIF1 hypermethylation in breast tumors." (PMID 25918249, 2015). "L breast tumors presented increased expression of the 3 DNMT types (non-normally distributed data, Welch unpaired T-test, DNMT1: p = 0.01; DMT3a: p = 0.04; DMT3b: p = 0.001)." (PMID 35123413, 2022). "Notably, there was a very good correlation between the inclusion of CD44 variant exons and the local levels of meDNA in three different cell types : HCT116/DKO, DNMT1-depleted HeLa cells and MCF10A-derived breast tumor cells." (PMID 34086943, 2021). "To investigate whether the difference in methylation profiles between breast tumors is related to differences in the DNA methyltransferase (DNMT) machinery, we compared the expression levels of DNMT1, DNMT3a and DNMT3b mRNAs between the high β and low β groups of breast tumors." (PMID 20830311, 2010).
viral infection (18 papers, 2010 to 2025). "The viral infection was associated with low DNMT1 expression at 72 h and 120 h post-infection." (PMID 39541416, 2024). "An increase in H3K27me3, histone modification repressive mark, is commonly observed after viral infection due to upregulation of the DNA (cytosine-5)-methyltransferase 1 (DNMT1)." (PMID 40507222, 2025). "The results showed that after viral infection, both DNMT1 and DNMT3A displayed a significant increase in expression (P < 0.005)." (PMID 26039376, 2015). "In particular, altered expression of DNMT1 is induced by diverse viruses including HIV-1, EBV, BKV and adenovirsuses; also, DNMT1 plays a pivotal role in the expansion of effector CD8+ T cell following viral infection." (PMID 20174570, 2010). "It was also observed that oxidative stress induced by viral infections, including SARS-CoV-2 infection, can inhibit the maintenance of DNA methyltransferase-1 (DNMT1), thereby aggravating the DNA methylation defects." (PMID 36992454, 2023). "The latent phase of the viral infection is also maintained by methylation of the RTA promoter, which is ensured by DNA methyl transferase 1 (DNMT1)." (PMID 29673190, 2018). "DNMT1 (MIM 126375) and MGMT (MIM 156569) are involved in DNA methylation and repair, respectively, two processes that are often dysregulated during viral infection." (PMID 20174570, 2010). "Additionally, BNIP3L was elevated in bacterial infection, potentially reflecting its role in mitophagy, while DNMT1, IFI27, SLFN5, and AHNAK were elevated in viral infection, and PABPC4 was elevated in KD." (PMID 39240972, 2024). "Actually, viral infection, chronic inflammation, and oxidative stress have been shown to affect DNMTs expression in HCC.Viral oncoproteins, such as the HCV core and the HBx protein of HBV, upregulate DNMT1 and DNMT3B." (PMID 32514254, 2020). "Here, we found that DNMT1 rather than DNMT3a or DNMT3b was involved in modification of DNA methylation during H5N1 virus infection; this is because expression of DNMT1 was inhibited upon virus infection, whereas that of the other two DNMTs changed little." (PMID 29717211, 2018).
dementia (16 papers, 2015 to 2024). Loss of intellectual abilities interfering with an individual's social and occupational functions. "Patients with hereditary sensory and autonomic neuropathy (HSAN1), noise-induced hearing loss (NIHL), dementia and cognitive decline have all been identified to carry DNMT1 mutations within various locations." (PMID 38970134, 2024). "In a recent report, DNMT1 mutations have been identified in four kindreds with hereditary sensory and autonomic neuropathy (HSAN1), characterized by dementia and hearing loss, but the precise function of DNMT1 in auditory organs remains uncovered." (PMID 35352419, 2022). "Mutations in DNMT1 caused hereditary sensory neuropathy with dementia and hearing loss." (PMID 39485681, 2024). "In addition to neuropathy, dementia, and hearing loss, patients with DNA methyltransferase (DNMT1) mutations present with mild CNS hypomyelination." (PMID 28451635, 2017). "For instance, CAMK2G and PDZD7 are involved in Usher Syndrome the most common condition leading to deafness and blindness, as well as DNMT1 has a role in DNMT1-Related Dementia, Deafness, and Sensory Neuropathy and LRTOMT in deafness." (PMID 28993790, 2017). "Hereditary sensory neuropathy with dementia and hearing loss (OMIM 614116), an adult-onset neurodegenerative disorder, is the first Mendelian inherited “methylopathy" identified due to mutations in the DNMT1 gene affecting the RFTS domain." (PMID 25815005, 2015). "The DNMT1:c.4001C>T was reported as VUS for Hereditary Sensory Neuropathy-Deafness-Dementia Syndrome (OMIM #614116), a degenerative disorder of the central and peripheral nervous systems characterized by sensorineural hearing loss, cerebellar ataxia, narcolepsy and dementia." (PMID 37674478, 2023). "In particular, PRNP, DNMT1 and APP play a role not only in the EOD but also in several other forms of dementia and brain diseases." (PMID 37819683, 2023). "We previously demonstrated that DNMT1 mRNA levels are not regulated in buffy coat samples from patients with AD, whereas DNMT3a expression is downregulated in buffy coats from dementia patients and in the brain of saline-treated APP/BIN1/COPS5 AD mice." (PMID 36432638, 2022). "We did not detect any significant change in DNMT1 expression between healthy subjects and PD or Dementia groups." (PMID 32210102, 2020).
triple-negative breast carcinoma (16 papers, 2015 to 2026). An invasive breast carcinoma which is negative for expression of estrogen receptor (ER), progesterone receptor (PR), and human epidermal growth factor receptor 2 (HER2). "Hypermethylation of the DNA methyltransferase 1 (DNMT1) gene is thought to be a cause of triple-negative breast cancer (TNBC)." (PMID 37394582, 2023). "Additionally, it was confirmed that DNMT1 is a key factor in the aggressivity of triple-negative breast cancer (TNBC)." (PMID 35327559, 2022). "The strategy to treat triple-negative breast cancers by targeting DNMT1 has been proposed recently." (PMID 27525019, 2016). "We consistently found that DNMT1 was highly expressed in luminal subtype, HER2 positive subtype and triple negative breast cancer tissues." (PMID 36273188, 2022). "The expression levels of DNMT1 and DNMT3A showed highest expression levels in triple negative breast cancer patients, where previous studies have observed hypermethylation of tumor suppressor genes." (PMID 33604794, 2021).
autosomal dominant cerebellar ataxia (15 papers, 2015 to 2025). A clinically and genetically heterogeneous group of neurodegenerative diseases characterized by a slowly progressive ataxia of gait, stance and limbs, dysarthria and/or oculomotor disorder, due to cerebellar degeneration in the absence of coexisting diseases. "In fact, DNMT1 mutations can lead to development of two neurodegenerative diseases known as autosomal dominant cerebellar ataxia-deafness and narcolepsy (ADCA-DN) and hereditary sensory neuropathy with dementia and hearing loss (HSN1E)." (PMID 33228792, 2020). "For instance, in exon 21 of the DNMT1 gene, de novo polymorphisms have been identified that underlie the deafness, narcolepsy, and ataxia that are seen in autosomal dominant cerebellar ataxia, deafness, and narcolepsy (ADCA-DN)." (PMID 39334883, 2024). "In this study, we describe a family with adult-onset autosomal dominant cerebellar ataxia with deafness and narcolepsy (ADCA-DN) caused by mutations in the maintenance methyltransferase DNMT1 and assess the DNA methylation profile of these individuals." (PMID 27602171, 2016). "Autosomal dominant cerebellar ataxia with deafness and narcolepsy (ADCA-DN, OMIM 604121) is a degenerative disease caused by mutations in the DNA-targeting domain of the maintenance methyltransferase DNMT1." (PMID 27602171, 2016). "To date, multiple studies have demonstrated that DNMT1 mutations could lead to a spectrum of neurodegenerative disorders, such as hereditary sensory and autonomic neuropathy type 1E (HSAN1E) and autosomal dominant cerebellar ataxia, deafness, and narcolepsy (ADCA-DN)." (PMID 34500587, 2021).
deafness (15 papers, 2014 to 2025). An inherited or acquired condition characterized by the complete loss of the ability to hear from one or both ears. "In line with this theory, our previous studies have identified specific epigenetic signatures for several disorders, including X-linked mental retardation with α-thalassemia, Floating-Harbor syndrome, DNMT1-associated cerebellar ataxia, deafness, and narcolepsy syndrome, as well as Kabuki syndrome." (PMID 29456765, 2018).
endometriosis (15 papers, 2012 to 2025). The growth of functional endometrial tissue in anatomic sites outside the uterine body. "In conclusion, we have demonstrated that endometriosis is associated with PR-B gene promoter hypermethylation, decreased PR-B expression, and increased DNMT1 and VEGF expression." (PMID 37370979, 2023). "In patients with endometriosis, DNMT1, DNMT3A, and DNMT3B are overexpressed in the epithelial component of endometriotic implants compared to normal controls or the eutopic endometrium of women with endometriosis." (PMID 40951281, 2025). "The involvement of altered DNMT1 expression in the onset of female infertility is confirmed by studies on endometriosis." (PMID 39594595, 2024). "To evaluate the potential value of DNMT1 and PR-B methylation as prediction tools of endometriosis with LBW history, we performed an ROC curve analysis." (PMID 37370979, 2023). "Our study showed that DNMT1 expression in endometrial eutopic tissue in the menstrual blood of women with endometriosis was significantly higher than in that of the control group (p < 0.001)." (PMID 37370979, 2023). "The cut-off value of both the DNMT1 expression and PR-B methylation were moderately correlated with the endometriosis incidence (r = 0.422 and r = 0.577, respectively)." (PMID 37370979, 2023). "To evaluate the potential value of DNMT1 and PR-B methylation as prediction tools for endometriosis with an LBW history, we performed an ROC curve analysis." (PMID 37370979, 2023). "Based on their findings, miR-200b-3p was linked to transcription factors such as DNA methyltransferase 1 (DNMT1), enhancer of zeste homolog 2 (EZH2), Hepatocyte nuclear factor-1-beta (HNF1B), MYB, JUN, ZEB1, and ZEB2 during endometriosis pathogenesis." (PMID 36289820, 2022). "miR-200b-3p was associated with the transcription factors DNMT1, EZH2, HNF1B, JUN, MYB, ZEB1, and ZEB2 during the pathogenesis of endometriosis." (PMID 32802844, 2020). "In a similar epithelial-based invasive pathology, of endometriosis, DNMT1, 3A, 3B are over-expressed in the ectopic endometrial cells." (PMID 24363660, 2013). "Concomitantly in endometriosis, DNMT1, 3A, 3B hypermethylate and down-regulate the anti-invasive HOXA10 gene expression in the eutopic endometrium." (PMID 24363660, 2013). "Moreover, it has also been previously reported that DNA methyltransferase-1 (DNMT1), an enzyme involved in DNA methylation, is overexpressed in endometriosis." (PMID 37370979, 2023). "Furthermore, to determine the relationship between the simultaneous effect of the DNMT1 expression and PR-B methylation cut-off values on the incidence of endometriosis with LBW, a multiple logistic regression analysis was performed." (PMID 37370979, 2023). "The p-values indicate that four genes (DIP2C, DNMT1, RRP1, and USP1) are significantly differentially hypomethylated in the endometriosis group compared to the control group." (PMID 39858463, 2025). "We found a significant positive correlation between PR-B methylation with DNMT1 expression in the non-endometriosis group with a history of LBW (r = 0.572; p = 0.041), meaning that the higher the PR-B methylation is the higher the DNMT1 expression will be." (PMID 37370979, 2023). "Then, DNMT1, EZH2, HNF1B, JUN, MYB, ZEB1, and ZEB2 were found as TFs related to endometriosis by interacting with target genes of miR-200b-3p." (PMID 32802844, 2020). "DNMT1, DNMT3A and DNMT3B transcripts in eutopic mid-luteal endometrium from infertile women with endometriosis, fertile women and infertile women with tubal occlusion." (PMID 22233680, 2012). "The four hypomethylated genes in endometriosis are RRP1, DIPC2, USP1, and DNMT1." (PMID 39858463, 2025). "Additionally, GRIK1-AS1 can impede DNMT1 from binding to the SRFP1 promoter, resulting in SFRP1 hypomethylation and subsequent upregulation, thereby accelerating the progression of endometriosis." (PMID 38408075, 2024).
endometriosis (continued). "Although not significant, our study showed a negative correlation between DNMT1 expression and PR-B expression among endometriosis women with LBW history." (PMID 37370979, 2023). "Our study aimed to analyze the risk of endometriosis in women with a LBW history and the relationships of progesterone receptor B (PR-B) gene promoter methylation, DNA methyltransferase-1 (DNMT1) expression, PR-B expression, and vascular endothelial growth factors (VEGF) with endometriosis." (PMID 37370979, 2023). "The DNMT1, DNMT3A, and DNMT3B expression levels were reported to be elevated in ectopic endometria compared to normal controls or in the eutopic endometrium of women with endometriosis." (PMID 32370117, 2020). "This might explain the significantly higher DNMT1 expression in the endometriosis group compared to the non-endometriosis group (p < 0.001)." (PMID 37370979, 2023). "Many studies reported the up-regulated expression of only for the DNMT3A and not for DNMT1 and DNMT3B in the endometriotic tissue which leads to hypermethylation in endometriosis." (PMID 32042366, 2020).
head and neck squamous cell carcinoma (15 papers, 2012 to 2025). A squamous cell carcinoma that arises from any of the following anatomic sites: lip and oral cavity, nasal cavity, paranasal sinuses, pharynx, larynx, and salivary glands. "However, head and neck squamous cell carcinoma (HNSCC) with advanced-grade tumors have high DNMT1 expression that is associated with better overall survival." (PMID 34572918, 2021). "In head and neck squamous cell carcinoma (HNSC), the presence of HNRNPC, DNMT1, DNMT3A, ZC3H13, NSUN5, and IGF2BP2 highlights potential cross-talk between DNA and RNA methylation in immune modulation." (PMID 40565233, 2025). "The GEPIA study reveals that, when compared with normal tissues, the expression of DNMT1 is elevated in CHOL, DLBC, head and neck squamous cell carcinoma (HNSC), pancreatic adenocarcinoma (PAAD), sarcoma (SARC), and thymoma (THYM)." (PMID 38666956, 2024).
pulmonary fibrosis (15 papers, 2014 to 2024). Chronic progressive interstitial lung disorder characterized by the replacement of the lung tissue by connective tissue, leading to progressive dyspnea, respiratory failure, or right heart failure. "Duaa’s study showed the hypermethylation of the miR-17–92 cluster promoter resulted in a significant downregulation of the miR-17–92 cluster in idiopathic pulmonary fibrosis patients, and the methylation level was upregulated by the DNMT1." (PMID 36451157, 2022). "MiR-19b, a member of miR-17-92 cluster, has been widely involved in cardiomyocyte proliferation and myocardial fibrosis, miR-19b expression is reduced in pulmonary fibrosis, which is involved in fibrosis through negative regulation of DNA methyltransferase-1." (PMID 31868204, 2020). "Interestingly, inhibition of DNA methylase levels (DNMT1, DNMT3a, and DNMT3b) promotes PPARγ expression and improves pulmonary fibrosis." (PMID 37986543, 2024). "In particular it has been shown that in patients affected by Idiopathic Pulmonary Fibrosis the miRNAs of the cluster are downregulated and Dnmt1 is upregulated with respect to control samples, thus suggesting that the disease could be associated to a switch of this DNFL." (PMID 25339974, 2014). "Overexpression of DNMT1, knockdown of lncRNA MEG3, autophagy inhibitor or ERK/p38 signaling pathway inhibitors reversed the positive effect of IL-27 in a lung fibrosis model in vitro." (PMID 36869378, 2023). "Previous report showed that the methylation of the miR-17-92 promoter was increased in pulmonary fibrosis and several miRNAs from the miR-17-92 cluster targeted DNMT-1 expression, resulting in a negative feedback loop." (PMID 30984146, 2019).